DNMT3B (DNA methyltransferase 3 beta)
Diseases named in the same sentence as DNMT3B in open-access papers (continued):
Sharing a sentence is not in itself a finding about the gene and the disease.
cancer (continued). "EZH2 was also shown to interact with DNMT1, DNMT3A, and DNMT3B in cancer cells and to result in the hypermethylation of genes, leading to increased permanent silencing of target genes." (PMID 39409007, 2024). "It is well-accepted that EZH2 catalyze H3K27me3 through interacting with DNMT1, DNMT3a and DNMT3b in cancer cells." (PMID 38992588, 2024). "A number of inhibitors targeting the ncRNA/DNMT3B axis have been developed with the aim of treating cancer." (PMID 37705098, 2023). "Significantly, the ncRNA/DNMT3B axis, such as miR-145/DNMT3B interaction, emerges as a noteworthy prognostic factor in human cancer." (PMID 37705098, 2023). "It has been shown that in human cancer cells, MiR-148 binds to DNMT3B and subsequently modifies DNMT3B splicing." (PMID 37107631, 2023). "In the current work, we emphasized the reciprocal regulation between ncRNAs, including lncRNAs, circRNAs, and miRNAs, and DNMT3B, which is frequently overexpressed during cancer progression." (PMID 37705098, 2023). "Combination therapy with histone deacetylases (HDACi) or (DNMT3B) inhibitors are currently under investigation for achieving a full cancer therapeutic potential." (PMID 36870998, 2023). "Resveratrol decreases DNMT1 and DNMT3B expression levels and modulates the aberrant expression profiles of microRNAs (miRNAs) in cancer cell lines and tumour tissues." (PMID 37111085, 2023). "In this review, we present a comprehensive overview of the ncRNAs/DNMT3B axis in cancer pathogenesis." (PMID 37705098, 2023). "An essential role for DNA methyltransferase DNMT3B in cancer cell survival has previously been illustrated." (PMID 37974198, 2023). "The human cancer condition involves dysregulation of the DNA methyltransferase 3 beta (DNMT3B) gene, a prominent de novo DNA methyltransferase, and its abnormal behavior serves as an indicator for tumor prognosis and staging." (PMID 37705098, 2023). "One such study has demonstrated that SFN combined with DIM significantly decreased the expression of DNMT1, DNMT3a, and DNMT3b in PC3, LnCAP, and PrEC cells, suggesting the de-methylation of the promoter region of cancer-associated genes." (PMID 36765652, 2023). "Further studies showed that overexpression of miR‐29b‐1‐5p inhibited DNMTs (DNMT1, DNMT3A, and DNMT3B) and promoted the expression of some cancer suppressor factors." (PMID 37901333, 2023). "Consistent with the correlation data, in the METABRIC series, only DNMT3B was significantly increased in BRCA1-like cancers compared with non-BRCA1-like samples." (PMID 37373065, 2023). "Certain genes have a double-edged role in cancer, as is the case with DNMT3B, thus it is worth exploring the further mechanism of DNMT3B’s role in cancer." (PMID 36091786, 2022). "Previous studies revealed that DNMT3b played a key role in establishing de novo DNA methylation and was upregulated in cancers." (PMID 35795047, 2022). "The studies with a wide approach on DNMT3B specific targets in human cancer are limited and most of them are made in human stem cells and animal models." (PMID 36460706, 2022). "An emerging body of evidence is forming in the literature that implicates the role of enzymes such as BRD4 and DNMT1/DNMT3B as epigenetic drivers of cancer and epithelial to mesenchymal transition." (PMID 35143483, 2022). "It is known that increased DNMT1 and DNMT3B expression play a significant role in the development and progression of several cancers, increasing the promotor methylation of several tumor suppressor genes." (PMID 36499741, 2022). "Truly, the expression of DNA methyltransferases DNMT1, DNMT3B and DNMT3A is often upregulated in different cancer cell lines and tissues, thereby causing the CpG islands hypermethylation of various tumor suppressor genes." (PMID 36366451, 2022). "Ostler suggests that aberrant DNA methylation patterns in cancer result from overexpression of catalytically inactive isoforms of DNMT3B." (PMID 36012258, 2022).
cancer (continued). "On the other hand, it was reported that Dnmt3b is involved in maintaining cytosine methylation in cancer." (PMID 36045397, 2022). "Our study found that RMI2 is related to DNA methylation in multiple types of cancer, among which BRCA, STAD, UCEC is associated with four DNA methylation genes (DNMT3L, DNMT3B, DNMT3A, DNMT1)." (PMID 35552266, 2022). "The consequences of some DNMT3B isoforms’ overexpression have been studied in several models of cancer cell lines, where DNMT3B4 and DNMT3B7 isoforms have activities such as growth suppressors, differentiation, and altering DNA methylation patterns." (PMID 36361550, 2022). "The global DNA methylation added by DNMT3B reflects its importance in cancer and is equally important to know specific genes downregulated by DNMT3B methylation." (PMID 36460706, 2022). "In our research, BCAT1 expression was correlated with the three DNA methyltransferase genes––DNMT1, DNMT3A, and DNMT3B in some cancers." (PMID 34984849, 2022). "DNMT3B targets genes in the cancer context and have been described to contain some cis elements associated with DNA methylation." (PMID 36460706, 2022). "It was suggested that they were upregulated in the cancer tissues, though, only DNMT3B expression showed a significant difference." (PMID 35129056, 2022). "In this review, we mainly summarize the roles of DNMT1, DNMT3A, and DNMT3B in cancer, hoping to shed new light on the treatment of cancer." (PMID 36091786, 2022). "We noted that EVA1B presented negative interactions with four major DNA methyltransferases containing DNMT1, DNMT2, DNMT3A, and DNMT3B in most cancer types." (PMID 35250982, 2022). "DNMT3B is the main de novo methyltransferase overexpressed in different types of cancer and has been described as necessary for tumor development." (PMID 36460706, 2022). "Significant correlations of BCAT1 expression with the three methyltransferases—DNMT1, DNMT3A, and DNMT3B—were detected in some cancers." (PMID 34984849, 2022). "This can be suggesting that abnormal DNA methylation in these carcinomas is a partial result of DNMT3B contribution and high DNMT3B levels are related to poor prognosis." (PMID 36460706, 2022). "In a data set from TCGA, we see that DNMT3B is the main de Novo methyltransferase overexpressed in epithelial carcinomas (6/6) with respect to DNMT3A (2/6)." (PMID 36460706, 2022). "DNA methylation is an important epigenetic mechanism regulating gene expressions through three DNA methyltransferases (DNMT1, DNMT3A, and DNMT3B) and affects cancer cell behaviors." (PMID 33612479, 2021). "DNMT1 is responsible for maintaining global methylation and aberrant CGI methylation in human cancer cells, whereas DNMT3a and DNMT3b are believed to act as maintenance and de novo methyltransferases." (PMID 33959155, 2021). "The relevance of DNMT3B overexpression in human cancer has also been questioned and apparent upregulation is suggested to reflect the greater proportion of cycling cells in tumour tissues." (PMID 33514701, 2021). "Resveratrol treatment has inhibited DNA methyltransferases (DNMTs) including DNMT1, DNMT3a, and DNMT3b expression and activity in human cancer cells." (PMID 34633989, 2021). "The m5C regulators with CNV amplification showed significantly increased expression in pan-cancers (such as DNMT3B), and m5C regulators with CNV deletion exhibited remarkably decreased expression, like TET2." (PMID 34325709, 2021). "Within community 2, we also identified increased expression of regulators of cell proliferation (CENPE, MKI67, TOP2A, UBE2C, guanine), cancer, and pluripotency (DNMT3B, DPPA4, MYC, POU5F1, CRABP2)." (PMID 33771987, 2021). "Taking into account that the overlapping DNMT3B-increased and H3K36me3-reduced peaks within regions relevant to transcription are assigned to genes enriched with cancer-driving functions and pathways, our results are in agreement with existing literature." (PMID 34439480, 2021).
cancer (continued). "DNMT3B was significantly up-regulated in all cancer cell lines, especially in EBV-positive cell lines." (PMID 34946098, 2021). "Horizontal analysis indicated that TET2, DNMT3B, DNMT3A, and DNMT1 demonstrated much higher mutation frequency among 33 cancers." (PMID 34325709, 2021). "In epithelial cancers, LMP1 indeed mediates the expression of host genes via DNA methylation through up-regulation of DNMT1, DNMT3A and DNMT3B, which further promotes the migration of cancer cells." (PMID 34946098, 2021). "Aberrant DNA methylation has been established as key molecular events contributing to tumorigenesis, and targeting DNMT1, DNMT3A, and DNMT3B with 5-azacytidine (Aza) and 5-Aza-2’-deoxycytidine were suggested as promising strategies for cancer treatment." (PMID 33589600, 2021). "DNMT3A and DNMT3B can actively add de novo methyl to DNA sequences to control gene expression and play a key role in cancer progression." (PMID 34722321, 2021). "UCEC exhibited a significantly higher number of mutations across pan-cancers, analogously TET2, DNMT3B, DNMT3A, and DNMT1 have placed a moderate burden in m5C regulator genes." (PMID 34325709, 2021). "NDRG2, another member of NDRG family which includes four members NDRG1-4, was reported to be significantly decreased in human cancers, and in GC, H. pylori silenced Ndrg2 by activating the NF-κB pathway and up-regulating DNMT3b, promoting GC progression." (PMID 34616614, 2021). "In our study, we also found that NFE2L2 expression was closely correlated with that of 4 DNA methyltransferases (DNMT1, DNMT2, DNMT3A, and DNMT3B) in human cancers, especially in COAD, KIRP, LGG, and UVM." (PMID 33101586, 2020). "Evidently, NFE2L2 expression is closely related to the expression of DNMT1, DNMT2, DNMT3A, and DNMT3B across human cancers, especially in COAD, KIRP, LGG, and UVM." (PMID 33101586, 2020). "Several reports have demonstrated that DNMT3a and DNMT3b are fre-quently overexpressed in cancers with poor prognosis, and targets of the miR-29 family, miR-101, miR-143, mir-148a and miR-152 have been reported in various forms of cancer." (PMID 33050637, 2020). "Among de novo DNA methyltransferases (DNMTs), DNMT3B has lately been reported to act specifically on actively transcribed genes, suggesting the possibility that it plays a role in the pathogenesis of cancer." (PMID 33277576, 2020). "Previous studies have indicated that DNMT3B is upregulated in various types of cancer, and DNMT3B overexpression is involved in gastric tumorigenesis." (PMID 33221743, 2020). "All together, these results indicate that piRNA-823 controls cancer stemness at least partially by DNMT3B activation." (PMID 30979371, 2019). "Only DNA methyltransferase (DNMT) genes were presented in results: DNMT1, DNMT3A, and DNMT3B were all highly expressed in 8, 6, and 9 cancer samples compared with normal, respectively." (PMID 31828117, 2019). "The pyrosequencing analysis revealed that a significant demethylation in the PTEN promoter occurred in TERT-depleted cancer cells, which was coupled with the DNMT3B down-regulation in these cells." (PMID 31284662, 2019). "Recently, it has been discovered that DNMT3B, in contrast to other methyltransferases, is necessary for gene remethylation and is also a potential therapeutic target to prevent cancer recurrence." (PMID 30718452, 2019). "El‐Osta reported that the methyltransferases Dnmt1 and Dnmt3b cooperatively maintain DNA methylation and gene silencing in human cancer cells." (PMID 31090214, 2019). "After scanning our oral cell lines, we observed that the mRNA expression of DNMT1 and DNMT3B was higher in most cancer cell lines compared with normal cell lines." (PMID 31624299, 2019). "The higher expression of DNMT3B led to poor prognosis in those cancer types, especially in KIRP with the maximum hazard ratio." (PMID 31828117, 2019). "Then, the survival analysis showed that high expression of DNMT3B had a poorer overall survival in 5 cancer types." (PMID 31828117, 2019).
cancer (continued). "We found some potential genes' methylation and expression in different cancer types influenced by DNMT3B whose expression is strongly relevant to the patient overall survival." (PMID 31828117, 2019). "Integrative altered methylation and expression revealed specific genes influenced by DNMT3B through DNA methylation across cancers." (PMID 31828117, 2019). "Our research clarifies some key metabolic genes, ACLY, SLC2A1, KAT2A, and DNMT3B, which are most disordered and indirectly contribute to the dysfunction of histone acetylation and DNA methylation in cancer." (PMID 31828117, 2019). "Earlier studies showed that knockdown of DNMT1 or double knockdown of DNMT1 and DNMT3B induces DNA demethylation in various cancer cells." (PMID 31064417, 2019). "ACLY, SLC2A1, KAT2A, and DNMT3B are the critical genes contributing to epigenetic dysfunction across cancers." (PMID 31828117, 2019). "Both hypermethylation and hypomethylation in gene promoters between high and low DNMT3B expression groups are found across cancers, which is consistent with the previous research." (PMID 31828117, 2019). "Inhibitions of DNMT3B as a novel therapeutic strategy for inhibiting the proliferation of carcinoma cells are being studied." (PMID 31828117, 2019). "To better understand the relevance of de novo DNMT expression in cancer biology, we began by exploring the mechanism and frequency of DNMT3A and DNMT3B deregulation across different human cancer types." (PMID 30468428, 2018). "Several studies have shown that DNMT3B is frequently upregulated and plays an important role in many cancers." (PMID 29796115, 2018). "Apart from the upregulation of TET2 and TET3, we also found that there is a significant downregulation of both DNMT3a and DNMT3b expression in cancer tissue compared with normal tissues." (PMID 29983831, 2018). "Whereas DNMT3A and DNMT3B are the de novo methylation enzymes, and their importance is correlated with the embryogenesis and pathogenesis of cancer cell." (PMID 30405408, 2018). "The PI3K/AKT signaling pathway has been reported to regulate DNMTs such as DNMT1 and DNMT3b at both the RNA and protein level in cancer cells." (PMID 29467020, 2018). "Altered DNMT3B expression levels result into variation in the targeting efficiency and abnormal catalytic activity contributing to cancer development and progression." (PMID 30406101, 2018). "Deregulation of the de novo DNA methyltransferase DNMT3B is frequently observed across cancer types, yet little is known about its ectopic genomic targets." (PMID 30468428, 2018). "Contrary to their canonical de novo methylation role, a series of experiments using DNMT genetic knockout cell lines suggest DNMT1 and DNMT3B cooperate to maintain methylation in human cancers." (PMID 30405408, 2018). "On the other hand, the levels of DNMTs, especially DNMT3a and DNMT3b, are often increased in various cancer tissues and cell lines such as HCT 116 cells." (PMID 28090275, 2017). "Several studies have been successfully conducted to suppress the expression of DNMTs especially DNMT3B in cancer cell lines." (PMID 28979331, 2017). "LSD2 overexpression also promotes the expression of DNMT3B, which is a critical epigenetic player in inducing aberrant DNA methylation and gene silencing in cancer." (PMID 29137219, 2017). "We have linked 5-aza hypersensitivity in EC cells to high levels of the DNA methyltransferase, DNMT3B and provided evidence to suggest that the relative insensitivity of somatic cancer cells to 5-aza is due to low DNA methyltransferase levels and activity." (PMID 27936464, 2017). "There are many studies that have demonstrated that a reduction of DNMT3b protein levels induces antiproliferative effects in human cancer cells which were attributed to the demethylation and reactivation of tumor suppressor genes." (PMID 29290961, 2017). "Inhibition of DNMT1, DNMT3a and DNMT3b has been reported to prevent tumor growth in many types of cancers." (PMID 28926997, 2017).
cancer (continued). "Together, these results suggest that the H19/SAHH/DNMT3B axis is active in multiple cancer types, where it can mediate metformin-induced hypermethylation of H19." (PMID 27775072, 2017). "In vitro, many cancers require DNMT3B for survival and proliferation, implying that DNMT3B can regulate proliferative pathways in a wide array of cancers." (PMID 28396701, 2017). "DNA methylation promotes the progression of cancer cells, and DNMT3B plays significant roles in hypermethylation and hypomethylation of genomic DNA." (PMID 27876061, 2016). "We confirmed overexpression of DNMT3A in six out of eight cancer types and DNMT3B overexpression in all cancer types, compared with normal tissues." (PMID 27121154, 2016). "Despite this complexity, a notable finding is that both DNMT1 and DNMT3b are required for silencing genes in cancer cells." (PMID 28039441, 2016). "Our results indicate that the inhibition of DNMT3B expression is a crucial step for reverting RMS cancer phenotype towards skeletal muscle differentiation, by restricting the expression of proliferative markers and up-regulating myogenic genes." (PMID 27764816, 2016). "Taken together, our data indicate that altered expression of DNMT3B plays a key role in ERMS development since its silencing is able to reverse cell cancer phenotype by rescuing myogenic program." (PMID 27764816, 2016). "Since different studies linked DNMT3B over-expression to gene-specific hypermethylation during cancer development and progression, we investigated the DNMT3B function in RMS." (PMID 27764816, 2016). "Altogether our findings also outline the potential clinical application of DNMT3B inhibition in cancer treatment." (PMID 27764816, 2016). "For instance, DNMTs (in particular DNMT3A and DNMT3B), which can potentially convert 5hmC to C, are frequently overexpressed in cancer." (PMID 26785262, 2016). "Together, these results suggested that DNMT3B dysfunction induced radiosensitization in cancer cell lines exhibiting high expression of DNMT3B." (PMID 26667181, 2015). "We showed that DNMT3B knockdown induces radiosensitization in DNMT3B expressing cancer cell lines, and in a xenograft model." (PMID 26667181, 2015). "DNMT3B is overexpressed in various cancer cells and DNMT3B overexpression is reported as a poor prognostic factor in patients." (PMID 26667181, 2015). "Downregulation of DNMT3B, one of the targets identified using this method, radiosensitizes cancer cells by disturbing multiple DNA damage responses." (PMID 26667181, 2015). "Altered DNA methylation is a common hallmark of cancer, and 200, 590, and 320 somatic mutations in DNMT1, DNMT3A, and DNMT3B, respectively, have been reported in the catalog of somatic mutations in cancers (COSMIC)." (PMID 25815005, 2015). "DNMT3A and DNMT3B are de novo DNMTs, which are highly expressed during embryogenesis and are usually deregulated in cancer cells." (PMID 25788984, 2015). "Here, knockdown of DNMT3B also increased the radiosensitivity of several cancer cell lines including HeLa cells to carbon-ion beam irradiation." (PMID 26667181, 2015). "Specific inhibition of DNMT1 or DNMT3b expression promotes growth arrest in cancer cells and attests to the relevance of DNMT expression-activity during malignant transformation." (PMID 25886188, 2015). "For DNMT3B −149C/T, the significance of pooled ORs was influenced evidently by individual study on the whole population or subgroup analysis of cancer type and ethnicity." (PMID 25433949, 2015). "More specifically, hypersensitivity was correlated with high expression of DNMT3b proper of embryonic and cancer stem cells." (PMID 24851905, 2014). "The levels of DNMTs, especially those of DNMT3A and DNMT3B, are often increased in various cancer tissues and cell lines." (PMID 24822169, 2014).